MIR4435-1 (microRNA 4435-1)
Synonyms: hsa-mir-4435-1; mir-4435-1
Gene: MicroRNA gene on chromosome 2 (87,629,755 to 87,629,834, forward strand). Ensembl gene ENSG00000265507.
Homologues: Orthologues: chimpanzee MIR4435-1 (100% identical).